SIAH2 (siah E3 ubiquitin protein ligase 2)
Diseases named in the same sentence as SIAH2 in open-access papers (continued):
Sharing a sentence is not in itself a finding about the gene and the disease.
Obesity (4 papers, 2017 to 2026). Accumulation of substantial excess body fat. "Brown fat from HFD-fed wild-type and Siah2KO males accumulated unilocular adipocytes with obesity, and brown fat whitening was increased further with Siah2 deficiency." (PMID 30987673, 2019). "The HFD-fed male Siah2-deficient mice are a model of metabolically healthy obesity, a phenotype more typically associated with females and attributed to the anti-inflammatory properties of estrogens." (PMID 30987673, 2019). "The impact of Siah2 on adipose tissue inflammation coupled with estrogen-mediated regulation of Siah2 gene expression prompted us to ask if there are sex-dependent effects of Siah2 deficiency on adipose tissue function in obesity." (PMID 30987673, 2019). "If so, then it would follow that the consequences of the reorganized rhythmic transcriptome in Siah2-/- females likely creates a chronic misalignment between metabolic and behavioral locomotor and feeding rhythms, a condition that often causes obesity and other metabolic disorders." (PMID 35789210, 2022). "Earlier studies of the impact of Siah2 deficiency carried out in a male mouse model of diet-induced obesity showed the ubiquitin ligase Siah2 functions at the intersection of adipose tissue inflammation and insulin resistance in obesity." (PMID 30987673, 2019). "These similarities suggest the mouse model of Siah2 deficiency may provide important and relevant mechanistic insights into sex-related differences in men and women in response to obesity." (PMID 30987673, 2019). "Estrogen-related regulation of Siah2, and its previously observed effects on white adipose tissue, prompted us to examine sex-dependent differences in white and brown adipose tissue inflammation in diet-induced obesity in a systemic Siah2-deficiency (Siah2KO) mouse model." (PMID 30987673, 2019). "However, since our data indicate that SIAH2 loss alters gene expression rhythms and the metabolism of lipids/lipoproteins specifically in female mice, we asked if SIAH2 loss similarly makes females more prone to developing obesity and other metabolic disorders when fed HFD." (PMID 35789210, 2022). "Global deletion of the ubiquitin ligase seven in absentia homolog 2 (SIAH2) improves glucose tolerance and insulin sensitivity while reducing adipose tissue inflammation with obesity." (PMID 41690475, 2026). "We found that while HFD-induced obesity led to development of diabetic-like changes in glucose homeostasis in males of both genotypes, this was largely unaffected in Siah2-/- females despite their increased obesity." (PMID 35789210, 2022). "In animal models SIAH2 appears to regulate obesity-related adipose tissue dysfunction and recruitment of immune cells to adipose tissue." (PMID 29135455, 2017). "In this way, this novel SIAH2-dependent circadian mechanism may contribute to resilience against diet-induced obesity in females and the overall sexual dimorphism in metabolism." (PMID 35789210, 2022). "Notably, adipocytes of SIAH2-deficient mice of both sexes fed HFD were larger in size than those of wild type mice, suggesting that the sex-specificity in obesity may be independent from SIAH2’s role in adipocyte development." (PMID 35789210, 2022). "Taken together, these data confirm that SIAH2-deficient females, but not males, have deficits in the mechanisms regulating lipid and lipoprotein metabolism that normally appear to contribute to preventing systemic dislipidemia and diet-induced obesity." (PMID 35789210, 2022).
lung adenocarcinoma (3 papers, 2014 to 2022). A carcinoma that arises from the lung and is characterized by the presence of malignant glandular epithelial cells. "We found that SIAH2 protein expression is significantly enhanced in human lung adenocarcinoma (ADC) and squamous cell lung cancer (SCC)." (PMID 26580787, 2015). "When we tested the impact of SIAH2 on the TK TYK2, we found that ectopic expression of SIAH2 in human embryonic kidney cells (293T cells) and in human lung adenocarcinoma H1299 cells strongly decreased the levels of TYK2." (PMID 24833526, 2014).
Parkinson disease (3 papers, 2020 to 2025). A progressive degenerative disorder of the central nervous system characterized by loss of dopamine producing neurons in the substantia nigra and the presence of Lewy bodies in the substantia nigra and locus coeruleus. "In this regard, Siah2 might work as a sensor of mitochondrial dysfunction in hypoxic conditions, thus activating the mitochondrial quality control process, as already described for the E3-ubiquitin ligase Parkin in Parkinson’s Disease." (PMID 39875361, 2025). "SIAH1, a member of the same family as SIAH2, has been reported to promote mitophagy through the PINK1-synphilin-1-SIAH1 signaling axis, contributing to the progression of Parkinson’s disease." (PMID 40004017, 2025).
cardiac hypertrophy (2 papers, 2018 to 2020). "Interestingly, Siah2-/- mice exhibited the same extent of cardiac hypertrophy estimated by LVW/BW compared to wt controls, as well as similar deterioration of cardiac function investigated by means of FS%, LVESd, and LVEDd." (PMID 29892230, 2018).
colorectal cancer (2 papers, 2024). A primary or metastatic malignant neoplasm that affects the colon or rectum. "In colorectal cancer, SIAH2 has been identified as an oncogene." (PMID 38393698, 2024).
Hyperglycemia (2 papers, 2017 to 2025). An increased concentration of glucose in the blood. "In the present study, we have shown that hyperglycemia promotes the degradation of HIPK2 in parte through ubiquitin ligase Siah2 downstream of a protein cascade including PP2A and HIF-1α, as summarized in the scheme." (PMID 27901482, 2017).
Insulin resistance (2 papers, 2019 to 2026). Increased resistance towards insulin, that is, diminished effectiveness of insulin in reducing blood glucose levels. "In the obese male mice, loss of Siah2 promotes lipid storage in hypertrophied adipocytes and reduces adipose tissue inflammation that leads to insulin resistance." (PMID 30987673, 2019). "Here, we generated a macrophage-specific SIAH2 deletion mouse model to assess the role of macrophage SIAH2 in the relationship between adipose tissue expansion and insulin resistance with a high-fat dietary challenge." (PMID 41690475, 2026). "Loss of SIAH2 in macrophages robustly increased glucose intolerance and insulin resistance without relative increases in body weight, serum lipids, or lipid accumulation in skeletal muscle or liver in male mice compared with WT male mice fed a high-fat diet but not a low-fat diet." (PMID 41690475, 2026).
ischemia (2 papers, 2017 to 2025). A hypoperfusion of the BLOOD through an organ or tissue caused by a PATHOLOGIC CONSTRICTION or obstruction of its BLOOD VESSELS, or an absence of BLOOD CIRCULATION. "D-AKAP1 is highly sensitive to proteolytic degradation via the E3 ubiquitin ligase Siah2 during ischemia." (PMID 29391924, 2017). "Interestingly, the genetic ablation of Siah2 by siRNA administration in preconditioned mice exposed to ischemia was able to counteract IPC-induced neuroprotection." (PMID 39875361, 2025). "Given that D-AKAP1 robustly and rapidly undergoes Siah2-mediated degradation during ischemia, it is conceivable that small molecular compounds that can coactivate PKA or stabilize endogenous levels of D-AKAP1 may confer significant protection during ischemia." (PMID 29391924, 2017).
liver cancer (2 papers, 2024 to 2025). An epithelial or non-epithelial malignant neoplasm that arises from the liver. "In this study, we observed a SIAH2‐induced inhibition of c‐JUN by downregulation of HBx, reversing the proliferative effect of this pathway on liver cancer cells." (PMID 38842124, 2024).
myocardial infarction (2 papers, 2016 to 2022). Gross necrosis of the myocardium, as a result of interruption of the blood supply to the area, as in coronary thrombosis. "In myocardial infarction, hypoxia activates SIAH2, which ubiquitinates AKAP121 and leads to its proteolysis." (PMID 35223093, 2022).
neuroendocrine prostate carcinoma (2 papers, 2015 to 2016). "Importantly, genetic knockout of Siah2 attenuated the development of neuroendocrine prostate carcinoma." (PMID 26580787, 2015).
diabetic foot ulcer (1 paper, 2025). "In this study, SIAH2 was identified as a key gene related to the progression of diabetic foot ulcer (DFU) wound healing." (PMID 41183121, 2025).
diabetics (1 paper, 2025). "Here, we showed the effect of efferocytosis in wound healing of diabetics and identified seven in absentia homolog 2 (SIAH2) as a potential efferocytosis-related biomarker." (PMID 41183121, 2025). "Our findings revealed that SIAH2 is highly expressed in the blood of patients with diabetes, and its expression in the skin at the ulcer area of patients with DFU is significantly higher than that in normal tissues." (PMID 41183121, 2025).
endothelial dysfunction (1 paper, 2015). In vascular diseases, endothelial dysfunction is a systemic pathological state of the endothelium (the inner lining of blood vessels) and can be broadly defined as an imbalance between vasodilating and vasoconstricting substances produced by (or acting on) the endothelium. "Nrf2 suppression by increased Siah2-driven proteasomal degradation mediates hypoglycemia-evoked endothelial dysfunction and loss of BBB integrity." (PMID 25807533, 2015). "In addition, we found that increased expression and cytosolic localization of Siah2 mediates hypoglycemia-induced Nrf2 down-regulation, leading to endothelial dysfunction and potential loss of BBB integrity." (PMID 25807533, 2015). "Overall, these findings reveal a more critical role for Siah2, rather than Keap1, as a molecular regulator of hypoglycemia-induced Nrf2 degradation and BBB endothelial dysfunction." (PMID 25807533, 2015).
epithelial ovarian cancer (1 paper, 2021). "Previous evidence indicates that the RING-domain E3 ubiquitin ligases including Cullin-RING E3 ligase complexes such as SCF complex (SKP1, Cullin and F-box protein), the APC/C complex, as well as monomeric XIAP, MDM2, MUL-1, Pirh2, and SIAH2 may all be associated with ovarian cancer chemoresistance." (PMID 35582023, 2021). "Some recent findings may explain the mechanisms through which SIAH2 mediates ovarian cancer chemoresistance." (PMID 35582023, 2021).
Hepatic steatosis (1 paper, 2022). Steatosis is a term used to denote lipid accumulation within hepatocytes. "Finally, SIAH2 loss also led to the development of HFD-induced hepatic steatosis, a trait in which wild type females were protected." (PMID 35789210, 2022).
Hyperinsulinemia (1 paper, 2020). An increased concentration of insulin in the blood. "Loss of SIAH2 did not protect against the development of hyperinsulinemia." (PMID 33396678, 2020).
Hypoglycemia (1 paper, 2015). A decreased concentration of glucose in the blood. "Nonetheless, our data demonstrate potential role for Siah2-dependent proteasomal degradation in hypoglycemia–induced Nrf2 suppression and loss of BBB integrity." (PMID 25807533, 2015). "Overall, these results suggest that increased activation of Siah2-dependent proteasomal degradation mediated hypoglycemia-elicited down-regulation of Nrf2 expression/stability in BBB endothelial cells." (PMID 25807533, 2015). "Given that hypoglycemia up-regulated protein and mRNA levels of Siah2, we next determined the relevant role of Siah2 and proteasome-dependent degradation, in hypoglycemia-induced Nrf2 down-regulation." (PMID 25807533, 2015). "In light of these findings, it is plausible that Siah2 silencing would elicit potential reduction of hypoglycemia-induced permeability to 4kDa dextrans." (PMID 25807533, 2015). "Although, Siah2 knock-down partially inhibited hypoglycemia-induced hyper-permeability to RITC labeled dextran, these effects were not significant." (PMID 25807533, 2015). "While hypoglycemic exposure triggered a significant increase in BBB permeability to dextrans, silencing Siah2 gene abrogated the effects of hypoglycemia and restored BBB integrity." (PMID 25807533, 2015). "Importantly, transient knockdown of Siah2 in hCMEC/D3 cells significantly blocked hypoglycemia-induced Nrf2 down-regulation, as demonstrated by IF analysis (P> 0.05, vs. scramble controls)." (PMID 25807533, 2015). "Thereby, strategies to inhibit increased Siah2 activity or augment Nrf2 activity could hold therapeutic potential to prevent hypoglycemia-induced cerebrovascular dysfunction." (PMID 25807533, 2015). "We speculate that siSiah2 could restore the clauin-5 TJ protein expression (that was suppressed by hypoglycemia,) as Siah2 knockdown restores hypoglycemia-induced Nrf2 down-regulation." (PMID 25807533, 2015). "Interestingly, Siah2 knockdown did not affect the dextran permeability under euglycemic conditions; however, transfection with Siah2 siRNA significantly decreased dextran hyper-permeability induced by hypoglycemia." (PMID 25807533, 2015). "However, results from this study raise interesting questions regarding the possible mechanisms involved in hypoglycemia-induced Siah2 expression and Siah2-Nrf2 interactions, which remain to be investigated further." (PMID 25807533, 2015). "Interestingly, hypoglycemia significantly increased the cellular pool and cytosolic localization of Siah2 with progression of time (3-24h, P < 0.05 at 12h) that correlates with up-regulation of Siah2 transcripts (~2.5 fold increase over control, P < 0.01)." (PMID 25807533, 2015). "Either, deletion of Siah2 or pharmacological blockade of 26S proteasome (a major pathway of Nrf2 degradation,) by MG132 restored hypoglycemia-induced Nrf2 function and BBB integrity." (PMID 25807533, 2015). "We provided a mechanistic insight in which increased expression of Siah2 (but not Keap1) by hypoglycemia targets endothelial Nrf2 for proteasomal degradation." (PMID 25807533, 2015). "Pretreatment with protease inhibitor MG132, or selective knock-down of Siah2 (but not Keap1) significantly attenuated hypoglycemia-induced Nrf2 destabilization." (PMID 25807533, 2015). "Interestingly, our data also suggested that Siah2 (but not other repressors such as Keap1) primarily contributed to hypoglycemia-induced suppression of Nrf2 protein in BBB, as knockdown of Keap1 expression did not alter hypoglycemia-induced Nrf2 suppression." (PMID 25807533, 2015).
Impaired glucose tolerance (1 paper, 2019). An abnormal resistance to glucose, i.e., a reduction in the ability to maintain glucose levels in the blood stream within normal limits following oral or intravenous administration of glucose. "The ubiquitin ligase Siah2 is an important mediator of the relationship between adipose tissue expansion via hypertrophy, adipose tissue inflammation, and impaired glucose tolerance in male and female mice that are chronically over-fed with a high-fat diet." (PMID 30987673, 2019).
infarct (1 paper, 2017). "For instance, Siah2 knockout mice exhibit little heart pathology after being subjected to ischemia reperfusion (e.g., myocardial infarct size)." (PMID 29391924, 2017).
invasive breast carcinoma (1 paper, 2011). A carcinoma that infiltrates the breast parenchyma. "In summary, we have shown that in situ and invasive breast carcinomas upregulate SIAH2 and that it is preferentially highly expressed in the basal-like subtype, which can be accounted for in part by increased gene copy number." (PMID 21306611, 2011).
invasive carcinoma (1 paper, 2011). A carcinoma that is not confined to the epithelium, and has spread to the surrounding stroma. "The increase in SIAH2 in in situ and invasive carcinomas correlates with the hypoxia that occurs in neoplasia as the metabolic demand of the tumor exceeds the supply of nutrients and oxygen from the disordered vasculature that is developing." (PMID 21306611, 2011).
leukemia (1 paper, 2021). A malignant (clonal) hematologic disorder, involving hematopoietic stem cells and characterized by the presence of primitive or atypical myeloid or lymphoid cells in the bone marrow and the blood. "Vitamin K3, an inhibitor of Siah2, promoted sensitivity of leukemia cells to imatinib." (PMID 33935743, 2021).
liposarcoma (1 paper, 2022). A usually painless malignant tumor that arises from adipose tissue. "This raises the possibility of posttranscriptional modifications that alter the relationship between SIAH2 mRNA and protein levels in the liposarcomas." (PMID 35313831, 2022). "SIAH2 protein levels did not define a clear distinction related to adipogenesis in these liposarcomas." (PMID 35313831, 2022).
multiple myeloma (1 paper, 2022). "While SIAH2 activity is associated with fundamental processes such as cell proliferation and apoptosis in hematologic malignancies, its oncogenic role in multiple myeloma was previously unclear." (PMID 36846090, 2022). "When analyzing HDAC3 and SIAH2 transcript expression profiles in 1,457 cancer cell lines, including 27 multiple myeloma cell lines, in the Cancer Cell Line Encyclopedia, we found that high levels of SIAH2 were associated with low HDAC3 expression." (PMID 36846090, 2022). "Our global analysis of SIAH2 transcript expression profiles in about 1,500 cancer cell lines indicates high expression of SIAH2 in multiple myeloma cells, suggesting a possible regulatory role in this cancer." (PMID 36846090, 2022). "Because SIAH2 directly interacts with HDAC3, it may derepress proliferative and metabolic genes and represent a target of clinical interest in multiple myeloma." (PMID 36846090, 2022).
myelogenous leukemia (1 paper, 2021). "Our results are supported by a mass spectrometry-based phosphoproteome analysis of a myelogenous leukemia cell line K562 which also identified the presence of Ser6-phosphorylated Siah2 in that cell but identifying the functional importance of phospho-Siah2 was not within the scope of that study." (PMID 33536006, 2021).
myocardial ischemia (1 paper, 2016). A disorder of cardiac function caused by insufficient blood flow to the muscle tissue of the heart. "Under myocardial ischemia, AKAP121 levels were reduced most likely as consequence of enhanced degradation by the hypoxia-induced E3 ligase Siah2." (PMID 27136357, 2016).
neuroendocrine tumors (1 paper, 2022). "Pdxp gene expression is increased in murine hepatic stellate cells cultured in hypoxia, in VHL-deficient murine endothelial fibroblasts and in neuroendocrine tumors lacking Siah2, a ubiquitin ligase that modulates HIF stability." (PMID 35251031, 2022).
pancreatic cancer (1 paper, 2022). "Furthermore, the qPCR results indicated the mRNA expression levels of JMJD6, ANKZF1, CITED2, and ENO3 was obviously decreased in pancreatic cancer cells versus the normal pancreatic ductal epithelial cells, whereas those of LDHA, TES, and SIAH2 were oppisite." (PMID 35935823, 2022).
preeclampsia (1 paper, 2010). Preeclampsia is a hypertensive disorder of pregnancy that is characterized by new-onset hypertension with proteinuria presenting after 20 weeks of gestation, and depending on mild or severe forms may initially present with severe headache, visual disturbances, and hyperreflexia. "In particular, we found decreased SIAH-1 and SIAH-2 mRNA levels in early-onset, but not late-onset, preeclamptic placentae, further emphasising the lack of placental oxygen sensing in the most severe form of preeclampsia." (PMID 20967267, 2010).
prostate adenocarcinoma (1 paper, 2010). "Recent studies indicate the importance of the ubiquitin ligase Siah2 in control of more aggressive prostate tumors – namely, neuroendocrine (NE) prostate tumors and prostate adenocarcinoma (PCa) harboring neuroendocrine lesions." (PMID 21037926, 2010).